CLOCK (clock circadian regulator)
Description:
Transcriptional activator which forms a core component of the circadian clock. The circadian clock, an internal time-keeping system, regulates various physiological processes through the generation of approximately 24 hour circadian rhythms in gene expression, which are translated into rhythms in metabolism and behavior. It is derived from the Latin roots 'circa' (about) and 'diem' (day) and acts as an important regulator of a wide array of physiological functions including metabolism, sleep, body temperature, blood pressure, endocrine, immune, cardiovascular, and renal function. Consists of two major components: the central clock, residing in the suprachiasmatic nucleus (SCN) of the brain, and the peripheral clocks that are present in nearly every tissue and organ system. Both the central and peripheral clocks can be reset by environmental cues, also known as Zeitgebers (German for 'timegivers'). The predominant Zeitgeber for the central clock is light, which is sensed by retina and signals directly to the SCN. The central clock entrains the peripheral clocks through neuronal and hormonal signals, body temperature and feeding-related cues, aligning all clocks with the external light/dark cycle. Circadian rhythms allow an organism to achieve temporal homeostasis with its environment at the molecular level by regulating gene expression to create a peak of protein expression once every 24 hours to control when a particular physiological process is most active with respect to the solar day. Transcription and translation of core clock components (CLOCK, NPAS2, BMAL1, BMAL2, PER1, PER2, PER3, CRY1 and CRY2) plays a critical role in rhythm generation, whereas delays imposed by post-translational modifications (PTMs) are important for determining the period (tau) of the rhythms (tau refers to the period of a rhythm and is the length, in time, of one complete cycle). A diurnal rhythm is synchronized with the day/night cycle, while the ultradian and infradian rhythms have a period shorter and longer than 24 hours, respectively. Disruptions in the circadian rhythms contribute to the pathology of cardiovascular diseases, cancer, metabolic syndromes and aging. A transcription/translation feedback loop (TTFL) forms the core of the molecular circadian clock mechanism. Transcription factors, CLOCK or NPAS2 and BMAL1 or BMAL2, form the positive limb of the feedback loop, act in the form of a heterodimer and activate the transcription of core clock genes and clock-controlled genes (involved in key metabolic processes), harboring E-box elements (5'-CACGTG-3') within their promoters. The core clock genes: PER1/2/3 and CRY1/2 which are transcriptional repressors form the negative limb of the feedback loop and interact with the CLOCK|NPAS2-BMAL1|BMAL2 heterodimer inhibiting its activity and thereby negatively regulating their own expression. This heterodimer also activates nuclear receptors NR1D1/2 and RORA/B/G, which form a second feedback loop and which activate and repress BMAL1 transcription, respectively. Regulates the circadian expression of ICAM1, VCAM1, CCL2, THPO and MPL and also acts as an enhancer of the transactivation potential of NF-kappaB. Plays an important role in the homeostatic regulation of sleep. The CLOCK-BMAL1 heterodimer regulates the circadian expression of SERPINE1/PAI1, VWF, B3, CCRN4L/NOC, NAMPT, DBP, MYOD1, PPARGC1A, PPARGC1B, SIRT1, GYS2, F7, NGFR, GNRHR, BHLHE40/DEC1, ATF4, MTA1, KLF10 and also genes implicated in glucose and lipid metabolism. Promotes rhythmic chromatin opening, regulating the DNA accessibility of other transcription factors. The CLOCK-BMAL2 heterodimer activates the transcription of SERPINE1/PAI1 and BHLHE40/DEC1. The preferred binding motif for the CLOCK-BMAL1 heterodimer is 5'-CACGTGA-3', which contains a flanking adenine nucleotide at the 3-prime end of the canonical 6-nucleotide E-box sequence. CLOCK specifically binds to the half-site 5'-CAC-3', while BMAL1 binds to the half-site 5'-GTGA-3'. The CLOCK-BMAL1 heterodimer also recognizes the non-canonical E-box motifs 5'-AACGTGA-3' and 5'-CATGTGA-3'. CLOCK has an intrinsic acetyltransferase activity, which enables circadian chromatin remodeling by acetylating histones and nonhistone proteins, including its own partner BMAL1. Represses glucocorticoid receptor NR3C1/GR-induced transcriptional activity by reducing the association of NR3C1/GR to glucocorticoid response elements (GREs) via the acetylation of multiple lysine residues located in its hinge region. The acetyltransferase activity of CLOCK is as important as its transcription activity in circadian control. Acetylates metabolic enzymes IMPDH2 and NDUFA9 in a circadian manner. Facilitated by BMAL1, rhythmically interacts and acetylates argininosuccinate synthase 1 (ASS1) leading to enzymatic inhibition of ASS1 as well as the circadian oscillation of arginine biosynthesis and subsequent ureagenesis. Drives the circadian rhythm of blood pressure through transcriptional activation of ATP1B1 (By similarity).
Synonyms: bHLHe8; KIAA0334; KAT13D
Tractability: PROTAC: UniProt records ubiquitination sites on it; ubiquitination databases record sites on it.
Safety:
Unwanted effects reported when the protein is acted on. In parentheses: how it was acted on, where the effect was seen, and who reports it.
sleep disturbances (source: ClinPGx)
Gene: Protein-coding gene on chromosome 4 (55,427,903 to 55,547,491, reverse strand). Ensembl gene ENSG00000134852.
Subcellular location: Nucleus; Cytoplasm; Cytoplasm, cytosol
Subcellular location (Human Protein Atlas): Nucleoplasm; Vesicles
Pathways (Reactome):
Circadian clock: BMAL1:CLOCK,NPAS2 activates circadian expression; Expression of BMAL (ARNTL), CLOCK, and NPAS2; Phosphorylated BMAL1:CLOCK (ARNTL:CLOCK) activates expression of core clock genes; Phosphorylation and nuclear translocation of BMAL1 (ARNTL) and CLOCK; Phosphorylation of CLOCK, acetylation of BMAL1 (ARNTL) at target gene promoters; The CRY:PER:kinase complex represses transactivation by the BMAL:CLOCK (ARNTL:CLOCK) complex
Cellular responses to stimuli: Heme signaling
Chromatin organization: HATs acetylate histones
Metabolism: PPARA activates gene expression
Gene Ontology:
Molecular function: DNA binding; E-box binding; histone acetyltransferase activity; protein binding; RNA polymerase II cis-regulatory region sequence-specific DNA binding; sequence-specific double-stranded DNA binding; chromatin DNA binding; DNA-binding transcription activator activity, RNA polymerase II-specific; DNA-binding transcription factor activity; DNA-binding transcription factor activity, RNA polymerase II-specific; sequence-specific DNA binding; protein dimerization activity; protein-lysine-acetyltransferase activity
Biological process: cellular response to ionizing radiation; circadian regulation of gene expression; DNA damage checkpoint signaling; positive regulation of circadian rhythm; positive regulation of DNA-templated transcription; protein acetylation; regulation of hair cycle; response to redox state; circadian rhythm; negative regulation of DNA-templated transcription; negative regulation of nuclear receptor-mediated glucocorticoid signaling pathway; photoperiodism; proteasome-mediated ubiquitin-dependent protein catabolic process; regulation of circadian rhythm; regulation of DNA-templated transcription; regulation of insulin secretion; regulation of transcription by RNA polymerase II; regulation of type B pancreatic cell development; signal transduction; spermatogenesis; chromatin remodeling; positive regulation of inflammatory response; positive regulation of transcription by RNA polymerase II
Cellular component: chromosome; CLOCK-BMAL transcription complex; cytosol; nucleoplasm; nucleus; chromatin; chromatoid body; cytoplasm; transcription regulator complex
Genetic constraint (gnomAD): Loss-of-function variants: 30 observed, 82 expected, observed/expected ratio (o/e) 0.37, 90% interval 0.27 to 0.5. The upper end of that interval is the gene's LOEUF score, 0.5, which puts it in group 2 of 6, group 1 being the genes least tolerant of losing a copy. Missense variants: 673 observed, 800.97 expected, observed/expected ratio (o/e) 0.84, 90% interval 0.79 to 0.89. Synonymous variants: 258 observed, 278.78 expected, observed/expected ratio (o/e) 0.93, 90% interval 0.83 to 1.03.
Homologues: Orthologues: chimpanzee CLOCK (100% identical), macaque CLOCK (99% identical), dog CLOCK (97% identical), mouse Clock (96% identical), guinea pig CLOCK (95% identical), rat Clock (95% identical), rabbit CLOCK (91% identical), pig CLOCK (91% identical), tropical clawed frog clock (78% identical), zebrafish clocka (71% identical), zebrafish clockb (61% identical), Drosophila melanogaster tgo (15% identical), and 3 more. Paralogues in human: NPAS2 (48% identical), ARNT (20% identical), ARNT2 (18% identical), BMAL1 (17% identical), BMAL2 (16% identical), PASD1 (15% identical).
Diseases named in the same sentence as CLOCK in open-access papers:
CLOCK is named in the same sentence as 196 diseases in open-access papers, as found by Europe PMC text mining. Sharing a sentence is not in itself a finding about the gene and the disease. The quoted sentences say what the papers report.
Obesity (88 papers, 2010 to 2025). Accumulation of substantial excess body fat. "Noteworthy, genetic polymorphisms within the core clock genes BMAL1 and CLOCK are associated with several cardiovascular metabolic diseases, namely hypertension, vascular atheromatosis, obesity and diabetes mellitus." (PMID 40283400, 2025). "Clock genes such as BMAL1, CLOCK, Per1, Per2, Cry1, and Cry2 have been implicated in various diseases, including hypertension, diabetes, and obesity." (PMID 39961935, 2025). "Disruption of WAT clocks—via high-fat diet or genetic ablation of BMAL1 or CLOCK—leads to impaired adipogenesis, altered hormone secretion, and increased risk of obesity and insulin resistance." (PMID 40510487, 2025). "Contrary to our findings, some research has indicated that adults with overweight or obesity who carry the minor allele of the CLOCK rs1801260 gene ate breakfast later." (PMID 39744380, 2024). "The CLOCK T > C polymorphism has been associated with obesity, sleep duration, response to weight loss." (PMID 39203789, 2024). "Researchers have found that differences in the CLOCK rs3749474, rs4580704, and rs1801260 gene variants are associated with chronotype, sleep patterns, obesity, dietary energy, and nutrient consumption." (PMID 39744380, 2024). "The circadian genes implicated in the stress-induced obesity are depicted as interacting in the following ways: CLOCK interacts with ARTNL and DBP." (PMID 39062927, 2024). "A significant correlation was observed between A-allele in CLOCK rs4864548 and an increased risk of obesity (OR: 1.97; 95% CI 1.22–3.10, p = 0.005)." (PMID 38612648, 2024). "In this view, our multivariate logistic regression model showed that CLOCK rs4864548 A-allele carriage was a strong risk factor for obesity." (PMID 38612648, 2024). "Variation in the CLOCK gene have been linked to an increased risk of obesity, type 2 diabetes, mood and sleep disorders, and several forms of cancer." (PMID 39203789, 2024). "In recent years, the relationship between CLOCK gene variants and obesity along with the underlying mechanisms have attracted attention." (PMID 39744380, 2024). "Studies have shown that genetic variations in the CLOCK genes are associated with chronotype, sleep patterns, obesity, dietary energy, and nutrient consumption." (PMID 39744380, 2024). "This indicates that a high-protein intervention alleviates liver CLOCK gene expression disruption caused by a high-fat diet or obesity." (PMID 37571396, 2023). "CLOCK C allele carries are more likely to experience higher energy intake, reduced sleep and later meal timings, and are more genetically susceptible to obesity if eating lunch after 3pm." (PMID 37664850, 2023). "Chronobiological misalignment and disrupted physiological rhythms has been repeatedly linked to obesity and genes previously shown to be associated with the regulation of circadian rhythm such as CLOCK are likely to play a crucial role." (PMID 37614712, 2023). "Loss of CLOCK results in reduced hepatic triglyceride accumulation following a high fat diet (HFD); whereas mice harbouring a CLOCK mutation (CLOCKΔ19) have dysregulated circadian rhythm, hepatic steatosis, obesity and metabolic syndrome." (PMID 37371052, 2023). "Rs1801260, a CLOCK polymorphism, has a role in the development of obesity, diabetes, and metabolic syndrome." (PMID 35276838, 2022). "Various studies have shown that CLOCK gene polymorphisms are associated with obesity and related diseases such as metabolic syndrome." (PMID 35655162, 2022). "Intriguingly, the associations between macronutrient intake patterns and obesity risks were different depending on the genotypes of CLOCK rs11932595, PER2 2304672, and CRY1 rs3741892." (PMID 35276838, 2022). "In conclusion, these findings suggest that macronutrient intake patterns were associated with obesity susceptibility, and the associations were different depending on the circadian clock genotypes of the CLOCK, PER2, and CRY1 loci." (PMID 35276838, 2022).
Obesity (continued). "Studies in animal models and in humans have shown associations between chronobiology and the prevalence of obesity, highlighting the involvement of the Circadian Locomotor Output Cycles Kaput (CLOCK) factor in metabolic dysfunction." (PMID 36079729, 2022). "After stratification by the genotypes of nine SNPs, the obesity risk according to the patterns was different according to the genetic variants of CLOCK, PER2, and CRY1." (PMID 35276838, 2022). "After the genotype stratification of nine SNPs of circadian genes, the association between the FC ratio and obesity risk differed by the genetic variants of CLOCK, PER2, and CRY1." (PMID 35276838, 2022). "Using general linear model (GLM), the association between CLOCK polymorphism (rs1801260) and obesity- related factors was investigated." (PMID 35655162, 2022). "In our study, carriers of the A allele of the rs1801260 variant of the CLOCK gene show a greater degree of obesity and significant lower weight loss and higher weight regain in the long term, regardless of the pre-surgery patient profile." (PMID 36079729, 2022). "The purpose of this study was to analyze the association between single nucleotide polymorphisms (SNPs) of CLOCK gene with obesity and with long-term weight response after different bariatric surgery (BS) techniques." (PMID 36079729, 2022). "Several mental and metabolic disorders in humans are associated with dysregulation of CLOCK and its related genes, including major depressive disorder, bipolar disorder, schizophrenia, diabetes mellitus and obesity." (PMID 35573988, 2022). "The Circadian Locomotor Output Cycles Kaput (CLOCK) gene has been linked to metabolic dysfunction and obesity." (PMID 36079729, 2022). "The CLOCK protein has also been associated with diabetes and obesity due to a mutation that prevents CLOCK from binding to DNA and activating target genes." (PMID 34066863, 2021). "CLOCK rs1801260 polymorphisms have been suggested to be associated with obesity, depression and Parkinson’s disease." (PMID 34068889, 2021). "Specifically, it was reported associations between single nucleotide polymorphisms in ARNT and T2DM, specific haplotypes of CLOCK and obesity, and between polymorphisms in CRY2 and elevated fasting glucose." (PMID 33815298, 2021). "In turn, the results of some studies on a potential association of SNP 3111T/C of the CLOCK gene and obesity showed that gender and age are important factors influencing the outcome." (PMID 35366265, 2020). "For example, the CLOCK single nucleotide polymorphisms (SNPs) rs4580704 C > G has been associated with obesity, hyperglycemia, and hypertension." (PMID 32466599, 2020). "In humans, two single nucleotide polymorphisms (SNPs) of CLOCK were reported to enhance the risk of overweight or obesity by 1.8-fold." (PMID 32164209, 2020). "Compared to the limited studies on the CLOCK SNP, the SNP, rs9939609, within the first intron of the fat mass and obesity-associated (FTO) gene has been widely investigated for its association with childhood obesity." (PMID 32785234, 2020). "A significant interaction between evening intake of carbohydrates of the volunteers and the rs3747494 CLOCK polymorphism when predicting BMI was identified, suggesting new alternatives of personalized nutritional treatment for obesity." (PMID 32325849, 2020). "It should be noted that the researchers did not differentiate their groups by gender, although it has been found that 3111T/C SNP of the CLOCK gene is associated with the risk of overweight/obesity only in women." (PMID 35366265, 2020). "The circadian desynchronization can be implemented using a homozygous CLOCK mutation model, which presents attenuated diurnal rhythm of feeding behavior and obesity." (PMID 33425971, 2020).